ACVR1 (activin A receptor type 1)
Diseases named in the same sentence as ACVR1 in open-access papers (continued):
Sharing a sentence is not in itself a finding about the gene and the disease.
fibrodysplasia ossificans progressiva (continued). "Previously only reported in a congenital autosomal dominant disease of the connective tissue called fibrodysplasia ossificans progressiva (FOP), ACVR1 mutations result in ligand-independent constitutive activation of the BMP signaling pathway." (PMID 26175967, 2015). "Small molecule inhibitors of the bone morphogenetic protein (BMP) receptor kinase ALK2 (ACVR1) are needed urgently to treat the progressively debilitating musculoskeletal disease fibrodysplasia ossificans progressiva (FOP)." (PMID 23646137, 2013). "The most striking and severe clinical manifestation of hyperfunctioning BMP signaling is Fibrodysplasia Ossificans Progressiva (FOP), caused by mutation in the ACVR1/Alk-2 gene that encodes the ACVR1/ALK-2 type I receptor." (PMID 23227223, 2012). "The ACVR1/Alk-2 gene, encoding a BMP type I receptor, is mutated in Fibrodysplasia Ossificans Progressiva, a severe form of heterotopic ossification." (PMID 23227223, 2012). "Furthermore, constitutive activating mutations of the type I BMP receptor, Acvr1, have been identified in the human syndrome Fibrodysplasia ossificans progressiva (FOP)." (PMID 21645366, 2011). "Fibrodysplasia ossificans progressiva (FOP) is an ultra-rare autosomal dominant disorder characterized by congenital malformation of the great toes and progressive heterotopic ossification of soft tissues, caused by mutations in the ACVR1 gene." (PMID 41970064, 2026). "The most common cause (>98 %) is Fibrodysplasia Ossificans Progressiva (FOP), a condition of extra skeletal bone formation caused by gain-of-function variants in the ACVR1 gene, which encodes a bone morphogenetic protein (BMP) type 1 receptor (Activin A Receptor Type 1)." (PMID 38879467, 2024). "The role of ACVR1 in human diseases was first described in fibrodysplasia ossificans progressiva (FOP)." (PMID 38201581, 2023). "Somatic mutations in ACVR1 are unique to DMG, with analogous germline mutations seen in fibrodysplasia ossificans progressiva (FOP)." (PMID 34759345, 2022). "Fibrodysplasia ossificans progressiva (FOP) and diffuse intrinsic pontine glioma (DIPG) are debilitating diseases that share causal mutations in ACVR1, a TGF‐β family type I receptor." (PMID 34003511, 2021). "Fibrodysplasia ossificans progressiva (FOP) and diffuse intrinsic pontine glioma (DIPG) are devastating human diseases, both associated with activating mutations in ACVR1, a type I TGF‐β family receptor." (PMID 34003511, 2021). "Fibrodysplasia ossificans progressiva (FOP), a hereditary form of HO, is caused by gain of function mutations in the BMP type 1 receptor ACVR1 (ALK2) with R206H being the most common point mutation located in the intracellular glycine-serine (GS) rich domain." (PMID 33410098, 2021). "Fibrodysplasia ossificans progressiva (FOP), an ultra-rare and disabling genetic disorder of skeletal malformations and progressive heterotopic ossification, is caused by heterozygous activating mutations in activin A receptor, type I/activin-like kinase 2 (ACVR1/ALK2)." (PMID 29482508, 2018). "This would be a significant boon, as LDN-193189 has already been used in rodent models of hepcidin-induced chronic anemia and fibrodysplasia ossificans progressiva (FOP) with constitutive activation of ACVR1, a type 1 BMP receptor kinase." (PMID 25544748, 2014). "Noggin mutations have also been reported in fibrodysplasia ossificans progressiva (FOP), which is a rare autosomal dominant disorder of skeletal malformations and progressive extraskeletal ossification caused mainly by mutations in the BMP type I receptor ACVR1." (PMID 21310029, 2011). "Fibrodysplasia ossificans progressiva (FOP, OMIM #135100) is a devastating and disabling bone disorder caused by a single codon gain-of-function variant in the type 1 bone morphogenetic protein-encoding gene ACVR1." (PMID 39456213, 2024).
fibrodysplasia ossificans progressiva (continued). "Cellular immunoprecipitation confirmed similar binding of FKBP12 and FKBP12.6 to the BMP receptor ALK2 (ACVR1), a known target of mutations in the congenital syndrome fibrodysplasia ossificans progressiva (FOP), as well as the pediatric brain tumor diffuse intrinsic pontine glioma (DIPG)." (PMID 33572801, 2021). "The genetic disorder fibrodysplasia ossificans progressiva (FOP) provides a unique window into ACVR1/Activin A signaling because in that disease Activin can either signal through FOP-mutant ACVR1 or form NSCs with wild-type ACVR1." (PMID 32515349, 2020). "This NSC is unique in that its stoichiometry is identical to that of corresponding signaling complexes formed between the same receptors and BMPs, but also in that it is converted into a signaling complex in the ACVR1-driven genetic disorder fibrodysplasia ossificans progressiva (FOP)." (PMID 32515349, 2020). "Indeed, patients carrying germline ACVR1 mutations that overlap with those found in DIPG develop fibrodysplasia ossificans progressiva (FOP), but not DIPG." (PMID 32142668, 2020). "Fibrodysplasia ossificans progressiva (FOP) is an extremely rare congenital form of heterotopic ossification (HO), caused by heterozygous mutations in the activin A type I receptor (ACVR1), that encodes the bone morphogenetic protein (BMP) type I receptor ALK2." (PMID 31768489, 2019). "Activin receptor-like kinase 2 (ACVR1/ALK2) regulates bone morphogenetic protein signaling, and ALK2 modulation has been identified as a promising therapeutic strategy for conditions including fibrodysplasia ossificans progressiva (FOP), diffuse intrinsic pontine glioma (DIPG), and glioblastoma." (PMID 42076879, 2026). "Lastly, it has been reported that endothelial cells expressing mutant activin 1 receptors (ACVR1) can trans differentiate into osteoblasts, an event that may be critical in the pathogenesis of a devastating disease such as Fibrodysplasia Ossificans Progressiva (FOP) (30, –32)." (PMID 23847596, 2013). "Expression of ACVR1, a BMP receptor involved in Fibrodysplasia Ossificans Progressiva (FOP), the genetic form of HOs, was not altered by any experimental conditions." (PMID 37700159, 2023). "Currently, no effective therapies exist for fibrodysplasia ossificans progressiva (FOP), a rare congenital syndrome in which heterotopic bone is formed in soft tissues owing to dysregulated activity of the bone morphogenetic protein (BMP) receptor kinase ALK2 (also known as ACVR1)." (PMID 33705358, 2021).
diffuse intrinsic pontine glioma (28 papers, 2015 to 2026). A neuroglial tumor that arises from the middle portion of the brain stem. "Mutations in the ACVR1 gene encoding for ALK2 occur in 25–33 ​% of patients with the rare pediatric cancer diffuse intrinsic pontine glioma (DIPG), with many being gain-of-function over-activating mutations." (PMID 39665954, 2024). "Additional disorders, such as diffuse intrinsic pontin glioma, diffuse idiopathic skeletal hyperostosis, primary focal hyperhidrosis, and congenital heart defects, have also been found to be associated with ALK2/ACVR1." (PMID 34206903, 2021). "Similar somatic mutations in ACVR1 are also observed in 25% of cases of diffuse intrinsic pontine glioma (DIPG), a rare childhood brain tumour." (PMID 28918311, 2018). "This is the case of tuberous sclerosis 1/hamartin (TSC1) or tuberous sclerosis 2/tuberin (TSC2) mutations occurring in subependymal giant cell astrocytomas, as well as H3 histone family member A/B (HIST1H3A/B) and activin receptor type 1 (ACVR1) mutations in diffuse intrinsic pontine gliomas." (PMID 31968687, 2020). "ACVR1 and H3.1K27M mutations co-occur in diffuse intrinsic pontine glioma." (PMID 30833574, 2019). "This hypothesis is supported by the observation that ACVR1 mutations are associated with a mesenchymal gene expression profile in diffuse intrinsic pontine glioma." (PMID 29164272, 2018). "For example, DMGs with mutations in the Activin A receptor 1 (ACVR1) gene, known as diffuse intrinsic pontine glioma (DIPG)-like ACVR1-mutant gliomas, were identified as a distinct molecular subgroup within DMGs." (PMID 37835563, 2023). "In addition, the presence of somatic mutations in ACVR1 is reported in 1 out of 4 pediatric patients with diffuse intrinsic pontine glioma (DIPG), a brain tumor that occurs in children and affects the brainstem." (PMID 38136984, 2023). "In diffuse intrinsic pontine glioma (DIPG—also called diffuse midline gliomas), H3K27M mutations, as well as ACVR1, FGFR1, MET, and PIK3CA mutations, were clonal." (PMID 33673104, 2021). "Diffuse intrinsic pontine glioma (DIPG) is an incurable pediatric brain tumor, with approximately 25% of DIPGs harboring activating ACVR1 mutations that commonly co-associate with H3.1K27M mutations." (PMID 30833574, 2019). "Diffuse intrinsic pontine glioma (DIPG) is a lethal childhood brainstem tumour, with a quarter of patients harbouring somatic mutations in ACVR1, encoding the serine/threonine kinase ALK2." (PMID 31098401, 2019). "This makes both ACVR1 and its downstream effectors interesting targets for the treatment of diffuse intrinsic pontine gliomas, especially when combined with other therapeutic modalities." (PMID 29164272, 2018). "Key recent findings include recurrent mutations in the genes encoding histones 3.3 and 3.1 (H3F3A and HIST1H3B) as well as the activin A receptor type I (ACVR1) that are unique to paediatric high-grade glioma (pHGG) and diffuse intrinsic pontine glioma (DIPG)." (PMID 29340109, 2017). "In contrast, in diffuse intrinsic pontine glioma (DIPG), a glial tumor in the brainstem with highly infiltrative properties in children, mutations in ACVR1 may exhibit pro-oncogenic functions." (PMID 35693928, 2022). "Additionally, recurrent heterozygous mutations of ACVR1 were associated with diseases in human such as fibro dysplasia ossificans progress (FOP), diffuse intrinsic pontine gliomas (DIPGs) and pediatric midline high-grade astrocytoma (mHGAs)." (PMID 33431058, 2021). "In addition to the R206H mutation, almost all ACVR1 mutations detected in FOP and diffuse intrinsic pontine glioma (DIPG) also presented enhanced responsiveness to BMP, resulting in higher SMAD1/5/8 signalling upon BMP stimulation." (PMID 31683698, 2019).
diffuse intrinsic pontine glioma (continued). "Diffuse intrinsic pontine glioma (DIPG) is a sever pediatric brain tumor, and it is the second disorder that has been shown to be associated with ALK2/ACVR1." (PMID 34206903, 2021). "More recently, ACVR1 has been experimentally validated as a cancer driver gene in diffuse intrinsic pontine glioma (DIPG), a malignant childhood brainstem glioma, and its function is being studied in other cancer types." (PMID 31683698, 2019). "Somatic mutations in ACVR1 are found in a quarter of children with diffuse intrinsic pontine glioma (DIPG), but there are no ACVR1 inhibitors licensed for the disease." (PMID 34551970, 2022).
anemia (26 papers, 2016 to 2026). A reduction in the number of red blood cells, the amount of hemoglobin, and/or the volume of packed red blood cells. "A phase 2 translational biology study demonstrated that anemia-related benefits of momelotinib are linked to its inhibition of ACVR1, which decreases hepcidin and improves iron metabolism." (PMID 39682253, 2024). "ACVR1 inhibition represents a viable target in the management of anemia associated with myelofibrosis." (PMID 38201581, 2023). "Anemia is a hallmark of MF and is the result of a complex and multifactorial process that includes upregulated expression of inflammatory cytokines, which in turn drive hyperactivation of activin A receptor type 1 (ACVR1)." (PMID 39682253, 2024). "Importantly, ACVR1 is associated with hepcidin expression, hematopoiesis and anemia via the BMP/ACVR1/SMAD pathway in MF." (PMID 38201581, 2023). "Momelotinib is an oral JAK1/JAK2/ACVR1 inhibitor approved in September 2023 for the treatment of patients with MF and anemia and is designed to address the complex drivers of iron-restricted anemia and inflammation associated with MF." (PMID 39682253, 2024). "Like all JAK inhibitors, momelotinib can improve constitutional symptoms and splenomegaly, but through its inhibition of ACVR1, it also provides anemia-related benefits." (PMID 39682250, 2024). "This post hoc descriptive analysis of the phase 3 SIMPLIFY-2 trial evaluated the relative benefits of this approach versus switching to the JAK1/JAK2/activin A receptor type 1 inhibitor momelotinib in patients for whom anemia management is a key consideration." (PMID 38990433, 2024). "Momelotinib, an inhibitor of JAK1, JAK2, and ACVR1, was approved in 2023 for the treatment of patients with myelofibrosis and anemia and has shown spleen and symptom benefits in phase 3 trials in this patient population." (PMID 38406514, 2024). "ACVR1 plays a vital role in the production of blood cells and the development of anemia by influencing the BMP6/ACVR1/SMAD pathway, which regulates the expression of hepcidin, a key controller of iron balance in the body." (PMID 38983933, 2024). "Inhibition of ACVR1 reduces hepcidin, releasing iron stores, thereby ameliorating inflammation-related anaemia, with ∼1 in 3 patients achieving an anaemia benefit." (PMID 39604140, 2024). "Momelotinib, an oral JAK 1/2 and activin A receptor type 1 (ACVR1) inhibitor, has shown clinical activity on symptoms, spleen, and anemia of patients with MF." (PMID 39110143, 2024). "Momelotinib, an oral Janus kinase (JAK) 1/2 and activin A receptor type 1 inhibitor, improved symptoms, splenomegaly, and anemia in patients with myelofibrosis (MF)." (PMID 39110143, 2024). "Other ACVR1 inhibitors (e.g., zilurgisertib) are evaluated in early phase clinical trials as treatments for anemia in MF patients." (PMID 38201581, 2023). "ACVR1 plays an important role in hematopoiesis and anemia via the BMP6/ACVR1/SMAD pathway, which regulates expression of hepcidin, the master regulator of iron homeostasis." (PMID 38201581, 2023). "Momelotinib, a JAK1/JAK2 inhibitor with additional activity against ACVR1, is in late-stage clinical development and is hoped to address the unmet need of anemia in patients with MF." (PMID 37345196, 2023). "On September 15, 2023, momelotinib (JAK1/2 and ACVR1 inhibitor) received FDA approval as a treatment for patients with intermediate- or high-risk MF and anemia based on the findings of the phase 3 trials, MOMENTUM (NCT04173494) and SIMPLIFY-1 (NCT01969838)." (PMID 38201581, 2023). "Approved ACVR1 inhibitors and other ACVR1 inhibitors in clinical development for the treatment of anemia in MF patients." (PMID 38201581, 2023). "Dual JAK1/2 and ACVR1 inhibition, such as in the case of momelotinib, provides enhanced therapeutic efficacy in MF given that the cardinal features of the disease (anemia, splenomegaly, and systemic symptoms) are concurrently treated with a single agent." (PMID 38201581, 2023).
anemia (continued). "Momelotinib is also type-I JAK1/2 specific inhibitor, similar to ruxolitinib, that was expected to improve symptoms of therapy-induced anemia by also inhibiting activin A receptor type 1 (ACVR1)." (PMID 35903543, 2022). "Momelotinib is a JAK1/JAK2 inhibitor, which in murine models of anemia in chronic disease, was shown to inhibit bone morphogenic protein receptor kinase activin A receptor type I (ACVR1)–mediated hepcidin expression, which stimulated erythropoiesis." (PMID 32198525, 2020). "Momelotinib, a JAK1/2 inhibitor, which also inhibits the activin A receptor type 1 (ACVR1) has shown significant improvement in anemia in treated MF patients." (PMID 32983162, 2020). "Zilurgisertib is an investigational inhibitor of activin receptor type 1 (ACVR1) that appears to improve anemia through reduction of hepcidin production by the liver and may become an important partner for ruxolitinib." (PMID 38441783, 2024). "In addition, an ACVR1/ALK2 inhibitor (BMP pathway) is being tested in combination with ruxolitinib in anemia of MF43,125." (PMID 37771602, 2023). "The underlying mechanism of pacritinib’s anemia benefits had not been elucidated until its inhibitory activity on the ACVR1/SMAD pathway and suppression of hepcidin expression were demonstrated in 2023." (PMID 38201581, 2023). "In line with its ACVR1-mediated inhibition of hepcidin expression, resulting in iron mobilization from cellular stores and enhanced erythropoiesis, momelotinib has provided a constellation of important benefits with respect to anemia in MF patients." (PMID 35045875, 2022). "Preclinical and clinical translational studies have demonstrated that MMB’s ability to improve anemia and transfusion dependency is linked to suppression of ACVR1/ALK2-mediated hepcidin production, which leads to increased serum iron availability and stimulation of erythropoiesis." (PMID 35869266, 2022). "The beneficial effects of MMB in addressing anemia and reducing the need for blood transfusions are associated with its ability to suppress the production of hepcidin mediated by Activin A receptor type I (ACVR1) also known as activin receptor-like kinase-2 (ALK2)." (PMID 38983933, 2024). "The JAK1/JAK2 inhibitor momelotinib, currently under investigation for patients with MF and anemia, has potent inhibitory activity against ACVR1/ALK2 and may become a second-line treatment option for patients who have to eventually stop ruxolitinib due to excessive anemia." (PMID 36786879, 2023). "More recently, momelotinib was approved for MF with anemia due to its dual JAK1/JAK2 inhibition and blockade of activin A receptor type 1 (ACVR1)." (PMID 41228192, 2025). "MMB’s unique inhibition of JAK1, JAK2, and ACVR1/ALK2, a key player in iron homeostasis, leads to decreased hepcidin and increased serum iron availability, contributing to considerable anemia benefits." (PMID 38983933, 2024). "Zilurgisertib (ACVR1 inhibitor) and DISC-0974 (anti-hemojuvelin monoclonal antibody) are evaluated in early phase clinical trials in patients with MF and anemia." (PMID 38201581, 2023). "Combining ACVR1 and JAK inhibitors is a promising strategy to target biological pathways that are critical in MF with symptomatic anemia." (PMID 38201581, 2023). "Momelotinib, an inhibitor of ACVR1/ALK2, JAK1 and JAK2, demonstrated activity against anemia, symptoms, and splenomegaly in the phase 3 SIMPLIFY trials." (PMID 35869266, 2022). "MMB inhibits ACVR1/ALK2, decreases hepcidin production, and ameliorates anemia of chronic disease in rodents, resulting in increased iron availability for erythropoiesis, which can potentially improve anemia." (PMID 39584924, 2024). "Importantly, in the past few years, several treatments for hepcidin dysregulation and anemia, including ACVR1/ALK2 inhibitors, were developed." (PMID 38201581, 2023).
anemia (continued). "Momelotinib acts by inhibiting the hyperactivated BMP6/ACVR1/SMAD pathway and suppressing hepcidin expression; thus, treatment with momelotinib results in higher circulating iron and Hb levels and improved erythropoiesis, which leads to significant anemia benefits in MF patients." (PMID 38201581, 2023).